MYH9 (myosin heavy chain 9)
Diseases named in the same sentence as MYH9 in open-access papers (continued):
Sharing a sentence is not in itself a finding about the gene and the disease.
tumor (continued). "HBx could also interact with non-muscle myosin heavy chain IIA (MYH9) and up-regulate it via modulating glycogen synthase kinase 3β (GSK3β)/β-catenin/c-Jun signaling pathway, contributing to promoted tumor stemness in HCC cells." (PMID 34456908, 2021). "Next, the rescue experiments confirmed that interfering with MYH9 significantly reduces tumor proliferation on CRLF1-overexpressing PTC cells but not in vector-expressing cells, in vitro, and in vivo." (PMID 32982961, 2020). "According to the PCR-array results, MYH9 was shown to take part in the process of ESCC migration through angiogenesis and EMT signaling pathways, while both angiogenesis and EMT are important factors in tumor development." (PMID 32788880, 2020). "MYH9 is a gene encoding nonmuscle myosin IIA (NMIIA), belongs to the myosin II subfamily, and it plays an essential role in invasion and metastasis of tumor cells." (PMID 32496549, 2020). "Inhibited MYH9 in PTC cells transfected with empty vector had no impact on the tumor migration and invasion ability." (PMID 32982961, 2020). "Furthermore, MYH9 expression restored the signals suppressed by FOXO1, including downregulation of GSK3β protein; however, it did not recover mRNA expression or stimulation of β-catenin and its downstream tumor stemness and EMT signals." (PMID 31754475, 2019). "A significant co-occurrence of an upregulation of the mRNAs of MYO10, MYH9, MYO1E and TGFB1 was observed in the LUSC patients of the TCGA cohort, suggesting that the exposure of tumor cells to elevated levels of TGFβ might have stimulated upregulation of motility and invasion-related myosins." (PMID 29934580, 2018). "In tumours, there may also be two or more proteins, which belong to different families, could combine with each other and is similar to the binding manner of ATG9B and MYH9, thus contributing to mutual stabilization of proteins promoting cascade amplification of tumour pathways." (PMID 34131310, 2021). "The lack of correspondence between exosomes and tumor tissues for VASP, LGALS3BP, MYH9 and LTBP1 could be due to the fact that these vesicles are loaded through active mechanisms." (PMID 37947594, 2023).
cancer (94 papers, 2013 to 2026). A tumor composed of atypical neoplastic, often pleomorphic cells that invade other tissues. "Together, our study reveals a novel mechanism by which SF3B1 mutation influences cancer progression via circRNA, and underscores the important role of MYH9 in organization of nuclear actin network." (PMID 41864997, 2026). "This review aims to present the structure, functional significance, and clinical associations of MYH9, with an emphasis on its contributions to MYH9-RD and cancer progression." (PMID 41953727, 2025). "The MYH9 gene is a well-known oncogene that is directly associated with progression, invasiveness, and drug resistance in many human cancers." (PMID 36900344, 2023). "Since cellular movements are closely associated with cancer progression and metastasis, the relationship between MYH9 and cancers has been investigated." (PMID 35318312, 2022). "MYH9 belongs to the myosin superfamily, which is closely associated with proliferation, migration, invasion and metastasis of cancer." (PMID 33959503, 2021). "Recently, MYH9 has been thought to be associated with cancer cell migration, invasion, and metastasis." (PMID 25826333, 2015). "Abnormalities of MYH9 and its associated proteins cause multiple types of diseases including cancers." (PMID 26134617, 2015). "Additionally, the dual role of MYH9 in MYH9-RD and cancer raises the intriguing question: are individuals with MYH9 mutations predisposed to or protected from cancer?" (PMID 41953727, 2025). "The MYH9 gene is increasingly associated with cancer, as evidenced by multiple recent studies." (PMID 39149512, 2024). "Besides the motorised protein impacts, differential expression of MYH9 has been implicated in cancer invasion and metastasis." (PMID 35125114, 2022). "To determine whether MYH9 function is related to molecular presentation in clinical cancers, we investigated the potential association of MYH9 expression levels with motility-related molecules using a TCGA-HNSC dataset." (PMID 36139430, 2022). "Therefore, it is reasonable to believe that a mutation of MYH9 plays an important role in the development of cancer." (PMID 32788880, 2020). "MYH9 participates in cell polarity, cell-cell adhesion, and cytoskeleton maintenance through its interaction with actin filaments and is involved in cancer invasion and metastasis." (PMID 39988672, 2025). "Targeting MYH9 through approaches such as non-coding RNAs, small molecules, or gene therapy presents a promising avenue for advancing cancer treatment." (PMID 41953727, 2025). "Considering the association of cancer stemness with metastasis and recurrence, we investigated the expression of PGK1 and MYH9 in recurrent and metastatic ESCC tissues." (PMID 40534132, 2025). "To ascertain the involvement of MYH9 in LR and cancer stemness of HCC cells, we further conducted a series of functional experiments." (PMID 39300073, 2024). "MYH9 promoted cancer cell chemoresistance, proliferation, and metastasis, as well as it was associated with poor poor patient prognosis." (PMID 38698330, 2024). "Meanwhile, MYH9 promotes the growth of other cancers, such as HCC, pancreatic cancer, gastric cancer, colorectal cancer, and breast cancer, and is associated with a poor prognosis in these patients." (PMID 38739940, 2024). "Elucidating MYH9’s mechanism of action can enhance the clinic’s ability to precisely stage tumors and evaluate prognosis across different cancer types, thereby improving the development of more effective therapeutic strategies for patients." (PMID 39149512, 2024). "The SNV landscape map revealed that the SNV of FLNA, FLNB, and MYH9 was frequently detected in various cancers." (PMID 38584831, 2024).
cancer (continued). "The results indicate that DKK4 expressed in CRC cancer cells strongly induces the formation of Vimentin+α-SMA+ fibroblasts and α-SMA+ MYH9+ myofibroblasts in cancer stromal tissues in mouse models." (PMID 38519641, 2024). "Current evidence shows that the effect of MYH9 on cancer is dualistic, and this gene can have different effects even in the same type of cancer." (PMID 38739940, 2024). "Given the unique role that MYH9 plays in tumors, it stands as a highly promising and effective target for cancer therapy." (PMID 39149512, 2024). "Further analysis revealed that circ-PRMT5 controls these effects by sponging miR-158-5p, supporting the expression of myosin heavy chain 9 (MYH9) which promotes cancer progression." (PMID 39703687, 2024). "The knockdown of MYH9 attenuates glycolysis and invasion, indicating its role in promoting cancer hallmarks under hypoxia." (PMID 39273383, 2024). "In recent years, an increasing number of studies have shown that MYH9 plays a significant role in cancer." (PMID 39149512, 2024). "hsa_circ_0000520 affected CRC cell function via the miR-542-3p/MYH9 axis, thus exacerbating cancer progression." (PMID 39641304, 2024). "MYH9 has been reported to play a crucial role in cancer cell proliferation, survival, invasion, and metastasis." (PMID 38902769, 2024). "Several studies have shown that MYH9 has a critical role in cancer and demonstrated that NMIIA expression in cancer cells associated with progression of various types of cancers." (PMID 37200287, 2023). "In particular, MYH9 was shown to interact with the calcium-dependent S100 family member S100A4 to promote the motility of human cancer cells." (PMID 36797800, 2023). "Each of these cases also carried other germline mutations (PBRM1, C7 and MYH9, BRCA1, ANKRD26) of which BRCA1 and ANKRD26 are cancer predisposition genes." (PMID 37869077, 2023). "MYH9 can promote cancer cell EMT and metastasis by regulating multiple signal transduction pathways." (PMID 37875476, 2023). "After protein mass spectrometry analysis of TM4SF1, we screened out the downstream protein MYH9, which, as a widely expressed cytoskeletal protein, was closely related to a variety of cancers." (PMID 37069693, 2023). "Other researches also shows that MYH9 was involved in cancer cells death resistance and promotes metastasis." (PMID 37740172, 2023). "Over the past several years, an increasing number of studies have shown that MYH9 is upregulated in various cancers." (PMID 37770914, 2023). "Taken together, MYH9 regulates multiple malignant phenotypes via various pathways, perhaps in a cancer type-specific manner." (PMID 36139430, 2022). "In DU145 cells, TUBB4A KO or MYH9 KD increased the expression of GSK3β but decreased the expression of nuclear β-catenin and its downstream targets, cyclin D1 and c-MYC, suggesting TUBB4A/MYH9-mediated GSK3β/β-catenin signaling in human cancer cells." (PMID 35589707, 2022). "MYH9 was overexpressed in tumors (p < 0.0001), supporting the oncogenic function of this molecule in cancer formation." (PMID 36139430, 2022). "MYH9, also known as myosin or non-muscle myosin heavy chain 9, is a 226 kDa subunit of class II conventional myosin that has been reported to play dual functions in cancers." (PMID 35650603, 2022). "We first showed that MYH9 contributes to radioresistance in cancer, accompanied by the regulation of antiapoptotic molecules." (PMID 36139430, 2022). "Many reports have shown that MYH9 is involved in the facilitation of cancer invasion or metastasis, as well as growth promotion." (PMID 36139430, 2022). "In the future, an in vivo study will be undertaken to support the therapeutic potential of targeting MYH9 for refractory cancer." (PMID 36139430, 2022). "The MYH9 (Myosin heavy chain 9), an architecture component of the actomyosin cytoskeleton, has been reported to be dysregulated in several types of cancers." (PMID 36139430, 2022).
cancer (continued). "By immunohistochemical staining of more tissue samples of acinar and ductal carcinoma of the pancreas, the correlation of MYH9 with cancer outcome and patients’ survival can be determined." (PMID 34425650, 2021). "In the literature, MYH9 has been described as a strong EMT inducer that promotes the progression of various cancers." (PMID 33664479, 2021). "In summary, this work demonstrates the dominant function of MYH9 in inducing cancer stemness and progression of HCC." (PMID 32296025, 2020). "MYH9 is a well-known cytoplasmic effector molecule in Rho-ROCK signaling pathways involved in cancer cell invasion and metastasis." (PMID 32685004, 2020). "Our findings highlight for the first time this correlation of NM IIA with cancer cell aerobic glycolysis by using MYH‐9 shRNA." (PMID 31397978, 2019). "Our findings highlight for the first time this correlation of NM IIA with cancer cell apoptosis by using the NM II inhibitor and MYH-9 shRNA." (PMID 27105508, 2016). "MYH9 is a member of the myosin superfamily and its function is related to migration, invasion and metastasis of cancer cells." (PMID 27822437, 2016). "The invasiveness of MCF-7/6 is decreased either by knockdown of MYH9 or treatment with blebbistatin, which inhibits the function of MYH9, indicating the involvement of MYH9 in the migration and invasion of cancer cells." (PMID 25826333, 2015). "Because MYH9 contributes to cell polarity, adhesion, division, and migration, several studies have indicated that MYH9 plays a key role in cancer cell migration, invasion, and metastasis." (PMID 25826333, 2015). "In recent years, MYH9 has gained significant attention for its pivotal roles in various cancers." (PMID 41953727, 2025). "MYH9 has been reported to play key roles in cancer through MAPK signaling pathway." (PMID 40456011, 2025). "Immunotherapies targeting MYH9 have also become relevant in cancer treatment." (PMID 39149512, 2024). "MYH9 also interacts with GSK3β and reduces its protein expression through ubiquitin-mediated degradation, thereby dysregulating the β-catenin destruction complex and inhibiting cancer stemness and EMT." (PMID 39550407, 2024). "In recent years, numerous studies have demonstrated the pivotal roles of MYH9 in various cancers." (PMID 39149512, 2024). "Our hypothesis is that cells experiencing disulfidptosis with increased expression of MYH9 could result in detrimental cancer outcomes, something we wish to avoid." (PMID 38739940, 2024). "Our previous studies have shown that MYH9 attenuated the GSK3β-mediated ubiquitination and degradation of β-catenin, thereby facilitating Wnt signaling activity and promoting proliferation, metastasis, and chemoresistance of cancer cells." (PMID 38698330, 2024). "MYH9 is involved in the generation of cell polarity, cell-cell adhesion processes and maintenance of the cytoskeletal structure by binding to actin filaments, and is also involved in invasion and metastasis in human cancers." (PMID 37875476, 2023). "We verified that TM4SF1 could activate the NOTCH signaling pathway by positively regulating MYH9, which ultimately promoted the cancer stemness in HCC and enhanced the drug resistance of HCC cells to Lenvatinib." (PMID 37069693, 2023). "Silencing MYH9 also inhibited SAMD9‐induced cancer stemness, angiogenesis, and EMT in ESCC cells." (PMID 36757050, 2023). "The study confirmed that TM4SF1 could regulate the NOTCH pathway by upregulating MYH9, thus promoting cancer stemness and Lenvatinib resistance in HCC." (PMID 37069693, 2023). "Lin X and his collaborators showed in a 2020 study that silencing MYH9 could inhibit cancer stemness in HCC." (PMID 37069693, 2023). "In addition, we demonstrated that SAMD9 stimulates MYH9 expression, cancer stemness, angiogenesis, and EMT by activating the β‐catenin pathway." (PMID 36757050, 2023). "In recent years, a growing body of researches has reported the deregulation of MYH9 in cancers." (PMID 35318312, 2022).
cancer (continued). "Previous studies have reported that MYH9 exerted paradoxical roles in different cancers." (PMID 35318312, 2022). "Myh9 promotes cancer cell growth and metastasis via activation of MAPK/AKT signaling in CRC." (PMID 36347835, 2022). "Subsequently, functional experiments showed that MYH9 promoted proliferation, migration of ccRCC cells in vitro and in vivo, which suggested that MYH9 might act as a cancer promoter in ccRCC." (PMID 35318312, 2022). "However, there were still many other investigations reported that MYH9 played the totally opposite role in other cancers." (PMID 35318312, 2022). "Recently, the altered expression of MYH9 has been reported in many types of cancer." (PMID 36139430, 2022). "Furthermore, an in vivo study is emergent to support the therapeutic potential of targeting MYH9 to better manage refractory cancers." (PMID 36139430, 2022). "The roles of FLNA and MYH9 in tumorigenesis and development have been reported in cancer." (PMID 34093822, 2021). "Previous studies indicated that the MYH9 performs diverse functions in different cancer types." (PMID 32982961, 2020). "Previous studies of MYH9 in cancers have been controversial 16-19." (PMID 32685004, 2020). "Indeed, in the LUSC patients of the TCGA cohort the second and third most regulated genes encoding myosins were MYH9 and MYO1E, which were previously implicated in cancer progression." (PMID 29934580, 2018). "Because MYH9 is reported to contribute to cell polarity and lamellipodia at the cell periphery and leading edge, strong staining intensity at the cell membrane may reflect the MYH9 activity in cancer cell migration and invasion." (PMID 25826333, 2015). "Among them, MYH9 was shown to provide an oncogenesis role in cancer cell migration." (PMID 24564330, 2013). "MYH9 could interfere protein stability in various types of cancers." (PMID 41345704, 2025). "By weakening MYH9-actin interactions and deactivating these molecular motors, it promotes the mitochondrial division process, resulting in an imbalance in mitochondrial dynamics and a significant inhibition of cancer cell survival, proliferation, and migration." (PMID 39149512, 2024). "Therefore, we hypothesized that TM4SF1 activated the NOTCH pathway by positively regulating MYH9, which in turn promoted cancer stemness in HCC." (PMID 37069693, 2023). "Hence, we hypothesized that TM4SF1 might affect the cancer stemness of HCC cells by regulating MYH9 and activating the NOTCH pathway." (PMID 37069693, 2023). "This means that MYH9 may be a promising target gene for cancer treatment." (PMID 36175877, 2022). "As MYH9 encodes the heavy chain of NMIIA, an architectural component of the actomyosin cytoskeleton, dysregulation of this gene may lead to cell invasion and cancer metastasis." (PMID 36139430, 2022). "Based on MYH9 protein role in cell polarity and protrusion of the lamelliapodia at the leading edge of the cell, it was suggested that membranous staining may be indicative of its role in cancer cell invasion and migration." (PMID 34425650, 2021). "Our findings reveal an additional layer of MYH9 regulation in ESCC, highlighting the complexity of its expression control in cancer cells." (PMID 40416600, 2025). "Taken together, our results revealed that in complex with MYH9 and MYH10, LAMC2 is essential for promoting ER-mitochondria interaction to alleviate ER stress and allow cancer cells to adapt and proliferate under stressful conditions." (PMID 37891404, 2024). "MYH9 promotes tumorigenesis in CRC by modulating MAPK/AKT signaling and influencing EMT, leading to aggressive cancer behavior." (PMID 39273383, 2024). "To examine the effect of LAMC2 on MYH9 and MYH10, we performed western blotting analyses using si-LAMC2 cancer cells, and showed that silencing LAMC2 significantly reduced the protein levels of MYH9, MYH10, as well as DRP1 and phosphorylated DRP1." (PMID 37891404, 2024).